ALB (albumin)
Diseases named in the same sentence as ALB in open-access papers (continued):
Sharing a sentence is not in itself a finding about the gene and the disease.
Hypercalcemia (continued). "The Youden index of the new formula surpassed that of the traditional albumin-corrected calcium formula, indicating its potential superiority in diagnosing hypercalcemia." (PMID 39544294, 2024). "For OS in NDMM patients, univariate analysis suggested that Age≥65, Albumin ≤ 35, Hypercalcemia, elevated LDH level, ISS III, R-ISS III, Gain 1q21, del 17p, MAF/IGH or MAFB/IGH, ASCT and VD/β-CTX at the time of MM diagnosis were risk factors." (PMID 37181039, 2023). "Five days later, the patient had to be readmitted due to severe symptomatic hypercalcemia (albumin-corrected Ca++ 4.43 mmol/L) combined with altered mental status, vomiting, constipation and acute prerenal failure (eGFR 36 mL/min/1.7 m2)." (PMID 36013138, 2022). "In our case woman, we would have initiated a specific drug treatment for hypercalcemia in case of albumin adjusted serum calcium concentrations above 3.5 mmol/L." (PMID 35745247, 2022). "The mean albumin-corrected serum calcium and urinary calcium-to-creatinine ratio were far below the cut-offs for hypercalcemia and hypercalciuria stated in the Methods section." (PMID 36364809, 2022). "The taking of 150,000 IU cholecalciferol in the PHPT group did not lead to a significant increase in hypercalcemia and hypercalciuria, which indicates the safety of this dose in patients with mild hypercalcemia (albumin corrected calcium <3 mmol/l)." (PMID 35018763, 2021). "Timely surgical intervention in the 2nd trimester has been associated with favorable outcomes in patients with moderate to severe hypercalcemia during pregnancy (calcium adjusted for albumin greater than 3 mmol/L (12.02 mg/dL))." (PMID 34209340, 2021). "The results from 565 Chinese MM patients in this study showed that the incidence of hypercalcemia was 11.31% (albumin-adjusted) or 7.42% (albumin with adjustment)." (PMID 33573678, 2021). "Once hypercalcemia is detected, serum albumin, ionized calcium, and 24-h urine collection for calcium excretion should be measured." (PMID 33505980, 2020). "Albumin‐adjusted sCa demonstrated a dose‐dependent, sustained response with complete control of FECa despite modest hypercalcemia at higher doses." (PMID 32212275, 2020). "Four patients had primary hyperparathyroidism with elevated levels of PTH and persistent hypercalcemia (albumin corrected or ionized calcium)." (PMID 31950464, 2020). "A recent study showed that albumin-corrected serum calcium level is likely to underestimate potential hypercalcemia in hemodialysis." (PMID 32286455, 2020). "In comparison with albumin-corrected calcium levels, hypercalcemia was less frequently observed when measured as free calcium in plasma." (PMID 31022222, 2019). "Other abnormal serum levels with regard to the cases are as follows: hyperproteinemia in 30%, low albumin/globulin (A/G) ratio in 54.2%, hypercalcemia in 11.3%, serum creatinine level of >2.0 mg/dL in 27.2% cases, and increased β2-microglobulin in 67%." (PMID 31355076, 2019). "Ionized calcium was chosen for these tests to provide a more specific diagnosis of pHPT in a low-range hypercalcaemia as compared to the formerly used albumin-corrected serum calcium values." (PMID 29532143, 2018). "A 72-year-old white woman was admitted to our hospital because of newly diagnosed hypercalcemia (albumin-corrected calcium 4.2 mmol/L; normal range 2.19–2.59 mmol/L) and multiple bone lesions visualized by bone scintigraphy." (PMID 28476174, 2017). "Of the 10,940 visits that included assessments of serum calcium, 189 (1.7%) had albumin corrected calcium levels exceeding 2.6 mmol/L (hypercalcemia)." (PMID 25372709, 2014). "Electrolytic disturbances were noted, namely, hypercalcemia (adjusted to the albumin levels) and hyperkalemia." (PMID 24895552, 2014).
Hypercalcemia (continued). "We report the case of a patient who presented with renal dysfunction, hypercalcemia, and albumin-globulin (A/G) reversal mimicking multiple myeloma, but further investigations, including imaging and tissue biopsy, ultimately established a diagnosis of sarcoidosis." (PMID 41685014, 2026). "A significant adverse effect associated with discontinuation of denosumab is hypercalcemia, which can be assessed most accurately by measuring plasma ionized calcium, and if not available, serum total calcium adjusted for albumin concentration can be used." (PMID 40547129, 2025). "Laboratory investigations revealed significant hypercalcemia (ionized calcium 1.69 mmol/L, total calcium unadjusted for albumin 3.44 mmol/L, 13.8 mg/dl), suppressed PTH (<1 pmol/L) and 1,25-dihydroxyvitamin D (<12 pmol/L) and PTH-related peptide was not high (0.9 pmol/L)." (PMID 40547129, 2025). "The diagnosis of hypercalcemia by albumin and globulin-corrected ionized calcium." (PMID 39544294, 2024). "The diagnosis of hypercalcemia by albumin-corrected ionized calcium." (PMID 39544294, 2024). "Compared with the actual hypercalcemia group and the pseudohypercalcemia group, the albumin level was higher in the actual hypercalcemia group than in the pseudohypercalcemia group (P <0.05), while the globulin level in the pseudohypercalcemia group was higher than in the actual hypercalcemia group." (PMID 39544294, 2024). "Comparing the new formula with the traditional albumin-corrected calcium, the albumin and globulin-corrected ionized calcium formula showed a sensitivity of93.75%, and a specificity of 96.85% for diagnosing hypercalcemia, with the Youden index of 0.906." (PMID 39544294, 2024). "Hypercalcemia (albumin-corrected Ca++ 4.21 mmol/L) was detected." (PMID 36013138, 2022). "Typical laboratory abnormalities including: reverse albumin/globulin ratio, monoclonal Bence Jones protein, proteinuria, hypercalcemia, decreased or normal alkaline phosphatase (ALP) unless there is a pathological fracture due to impaired osteoblastic function." (PMID 32845352, 2020). "However, after correcting calcium for serum albumin levels, 7 patients (46.7%) showed hypercalcaemia (> 2.58 mmol/l)." (PMID 30940121, 2019). "UK guidance only recommends the use of hypercalcaemia as a potential marker of myeloma, with no mention of albumin measurements, which may also explain the low cancer risk for patients with an abnormal test result." (PMID 40941010, 2025). "Notably, she had primary hyperparathyroidism (parathyroid hormone [PTH] 16.8 pmol/L [158.5 pg/mL], reference 1.6-6.9 pmol/L; [15.1-87.7 pg/mL]) and mild hypercalcemia (albumin-corrected calcium 2.76 mmol/L [11.06 mg/dL], reference 2.10-2.60 mmol/L; [8.4-9.5 mg/dL])." (PMID 39011405, 2024). "Their findings revealed a 24% prevalence of hypercalcemia at the time of DLBCL diagnosis, and this condition was strongly associated with high-risk features such as International Prognostic Index (IPI) components, B symptoms, elevated β2-microglobulin, and abnormal hemoglobin and albumin levels." (PMID 39677199, 2024). "Fifth, although corrected serum CaPO4 is commonly used in clinical practice, we noted that albumin-corrected calcium concentration might overestimate hypercalcemia compared to ionized calcium, which, despite its higher cost and lesser availability in our setting, might be more accurate." (PMID 39026574, 2024). "These two cases suggest that extracorporeal treatments with high cut-off hemodialysis and total plasma exchange with albumin may be considered as add-on treatment in refractory cases of vitamin D3-induced hypercalcemia to lower plasma 25-OH-vitamin D3 concentrations." (PMID 36547775, 2023). "For patients with severe hypercalcemia, the median LOS was 9.5 days when measured as free calcium and 5 days when measured as albumin-corrected calcium, respectively." (PMID 31022222, 2019).
Hypercalcemia (continued). "Despite the elevated serum total calcium and albumin-corrected calcium levels in our patient, no symptoms of hypercalcemia were observed." (PMID 40610015, 2025). "On admission, he was found to have an elevated albumin-corrected serum calcium of 13.6 mg/dL, a serum phosphorus of 2.2 mg/dL and an intact PTH of 6 pg/mL (normal 18–90) with a PTHrP of 8.1 pmol/L (normal < 4.3), consistent with PTHrP-dependent hypercalcemia." (PMID 37328745, 2023). "Hypercalcemia was very common, but relevant studies were relatively lacking, and multicenter large sample studies on albumin-corrected calcium and mortality in ICU patients are limited." (PMID 36619536, 2022). "The diagnosis of PHPT in pregnancy can be confirmed in the presence of hypercalcemia (elevated serum ionized calcium or calcium adjusted for albumin) with a non-suppressed parathyroid hormone (PTH) level." (PMID 34209340, 2021). "Hypercalcemia was noted in 11.2% of newly diagnosed MM patients when the serum calcium level was albumin-adjusted, but the incidence of hypercalcemia was 7.3% of newly diagnosed MM patients if the serum calcium level was not albumin-adjusted." (PMID 33573678, 2021). "Although albumin-corrected calcium levels > 2.55 mmol/L were observed, the proportion of participants with hypercalcaemia was not different between groups." (PMID 32162241, 2020). "In our study, some participants had calcidiol levels ≥ 100 nmol/L with or without hypercalcemia (albumin-corrected calcium levels > 2.55 mmol/L) at baseline or during the study." (PMID 32162241, 2020). "Similarly, the albumin‐adjusted sCa showed a dose‐dependent, sustained response that correlated with the Free PTH profile, with control of FECa despite mild hypercalcemia in the higher dose cohorts." (PMID 32212275, 2020). "It should be noted that ionized calcium levels were not evaluated; nevertheless, the selected cut-off value for hypercalcemia (10.5 mg/dL), and the comparable levels of serum albumin in the two groups argue for a true hypercalcemia." (PMID 31467367, 2019). "Serum albumin-corrected calcium levels during denosumab administration were stable in this cohort, with no hypercalcemia representing rebound inhibition of bone resorption." (PMID 30477250, 2018). "Three patients with no aberrant methylation had severe hypercalcemia (albumin-corrected serum calcium levels 14.6, 13.7 and 14.3 mg/dl)." (PMID 28600574, 2017). "There were no episodes of confirmed hypercalcemia according to the study definition, and no isolated albumin-adjusted [Ca] values greater than the recent IOM upper limit of normal of 2.63 mmol/L." (PMID 23268736, 2012). "On the contrary, CCI, serum baseline albumin, hypercalcemia and LDH did not impact OS." (PMID 37627065, 2023). "In MM patients, the reduction in albumin levels does not seem to depend on age and/or gender, nor does it appear to be affected by liver and kidney function, by the presence of bone osteolytic lesions, Bence−Jones proteinuria, hypercalcemia, and body weight." (PMID 36979941, 2023). "We personally consider albumin adjusted serum calcium concentrations from 3.0 to 3.5 mmol/L as a range in which specific drug treatments to lower calcium levels should be seriously considered if other measures are not effective and if symptoms or adverse consequences of hypercalcemia emerge." (PMID 35745247, 2022). "We find that adjustment of TCa for albumin does not outperform unadjusted values in the prediction of Ca2+ in an unrestricted dataset and that the relationship between PTH and calcium is strongest in the setting of hypercalcaemia." (PMID 37251673, 2023).
myeloma (77 papers, 2004 to 2026). "The combined assessment of eGFR, albumin, and β2-microglobulin provides a comprehensive view of multiple myeloma's systemic and organ-specific effects, guiding risk stratification and management strategies." (PMID 40369504, 2025). "Examining the blood test results in a large English primary care dataset demonstrated that having either low albumin or high calcium was predictive of cancer risk, and more specifically risk of myeloma." (PMID 40941010, 2025). "Multiple clinical factors, including age, sex, concomitant diseases, blood β2-MG, albumin, and G-band karyotype, are associated with the prognosis of multiple myeloma." (PMID 38831187, 2024). "This was followed by the much simpler, but robust, ISS in 2005, based on β2-microglobulin and serum albumin levels, which became the standard risk stratification for myeloma patients." (PMID 33154703, 2020). "The association between serum β2M and albumin upon patient prognosis in myeloma, not only is reminiscent of similar associations noted in the dialysis literature but also is very robust statistically." (PMID 28664159, 2017). "For the MMIn data, elevated levels of β2M and calcium with lower levels of eGFR and hemoglobin contributed to high risk, whereas in the MMRF data, elevated levels of β2M and lower levels of hemoglobin, eGFR, and albumin contributed to high risk in myeloma patients." (PMID 34858811, 2021). "Currently, most studies have confirmed that high serum β2-microglobulin, low albumin, high serum creatinine, high lactate dehydrogenase, low hemoglobin, low platelet count, high-risk cytogenetic abnormalities, and advanced age are adverse prognostic factors for multiple myeloma." (PMID 37109052, 2023). "Patients suffering from multiple myeloma or other immunoproliferative disease has been known to show gross divergences of serum proteins constitution in comparison with normal people, including hyperproteinemia and associated change in albumin-globulin ratio (AGR)." (PMID 29416697, 2018). "When the kidney function is normal, the beta-2 microglobulin seems to reflect the entire mass of myeloma cells and, in our study population, as expected, it is negatively related to albumin levels (p < 0.001)." (PMID 38310176, 2024). "URVIN was derived from peripheral blood of a terminally ill 52-year-old male myeloma patient with secondary plasma cell leukemia, and the clinical parameters measured at sampling were albumin: 32 g/L, and IgG-kappa: 2.8 g/L." (PMID 39567630, 2024). "The first is proliferation rate and disease severity indicated by albumin and its inverse relation with interleukin-6 – a known growth and survival factor of myeloma cells." (PMID 35211412, 2022). "In this study, we evaluated the anti-myeloma activity of 3 nanocomposites (3NPs): As4S4/ZnS/Fe3O4 (1:4:1), As4S4/ZnS/Fe3O4 with folic acid (FA), and As4S4/ZnS/Fe3O4 with FA and albumin with reduced survival MM cell lines and primary MM samples by each of 3NP." (PMID 36289430, 2022). "Common calorimetric markers feature the vast majority of the different myeloma types, i.e., stabilization of the major serum proteins and decrease in the albumin/globulin heat capacity ratio." (PMID 36010876, 2022). "We found that 1q21 gain is common (45.9%) at diagnosis in multiple myeloma, and this aberration is associated with later ISS stage levels, lower serum albumin levels, and elevated LDH concentrations, consistent with previous research results." (PMID 36185185, 2022). "The International Staging System, which is based on serum beta-2 microglobulin and albumin levels, is the most widely adopted in multiple myeloma and is also correlated with the prognosis of the disease." (PMID 34069672, 2021). "Multiple myeloma patients had lower levels of haemoglobin, albumin, and calcium when compared to healthy control volunteers (p = 0.045, p < 0.0001, and p < 0.0001)." (PMID 34522628, 2021).
myeloma (continued). "A single band was observed at approximately 370 kDa in the purified samples of the IgA-albumin complexes from the sera of multiple myeloma patients." (PMID 33578917, 2021). "on 1,027 MM patients showed that age, proportion of plasma cells, platelet count, serum albumin, and serum creatinine were the most important prognostic factors for multiple myeloma." (PMID 34867949, 2021). "In this study, we performed detailed molecular analyses of the IgA-albumin complex contained in the sera of the patients with multiple myeloma." (PMID 33578917, 2021). "In this study, we analyzed the prognostic significance of PLP2 expression in MM patients using IHC analysis and GEO datasets and correlated with markers of myeloma activity, such as lower serum levels of ALB, higher serum levels of β2-MG, LDH, and CRP." (PMID 32596309, 2020). "Utilizing albumin-bound rapamycin NPs, one can effectively increase the lifespan of an animal xenograft model of multiple myeloma." (PMID 30642006, 2019). "The International Staging System (ISS) published by the International Myeloma Working Group in 2005 introduced a new staging system using β2-microglobulin (β2M) and albumin levels as prognostic factors." (PMID 26053837, 2015). "Patients' characteristics were similar according to age, gender, renal functions, myeloma subtype, hemoglobin (G/dL), serum albumin, bone marrow plasma cell percentage, year of treatment, and absolute lymphocyte counts at diagnosis." (PMID 24777883, 2014). "On the other hand, higher levels of TT-specific antibodies were significantly associated with younger age (<60 years) and normal serum calcium and albumin as well as normal IgG concentrations in IgG myeloma." (PMID 22481961, 2012). "The International Staging System (ISS), based only on two laboratory variables, the β2-microglobulin and albumin serum concentrations, has replaced the Durie-Salmon staging system in 2005 and is currently considered standard for staging of myeloma." (PMID 21698234, 2011). "The prognosis in myeloma is determined by two factors: Beta2microglobulin and serum Albumin." (PMID 39329904, 2024). "Almost all patients with stage III myeloma had blood albumin concentrations of 37.0 g/L or less." (PMID 37370298, 2023). "In a multivariable proportional hazards Cox regression analysis adjusted according to demographic and clinical factors, we selected age, gender, eGFR,HB,LDH,RI, albumin, serum/urinary lambda or kappa light chains, serum beta 2-microglobulin, and anti-myeloma therapy regimen as confounding factors." (PMID 35756671, 2022). "Biomarkers for which patients may have very high values are, for instance, tumor markers, IgG, IgA, IgM, FLC (myeloma patients), and urine albumin." (PMID 36304451, 2022). "Oxidized albumin has been associated with the pathophysiology of complications of multiple myeloma, although the etiology of these diseases is not fully understood." (PMID 33578917, 2021). "Multiple myeloma patients had significantly reduced haemoglobin (9.3 ± 2.4 g/dL in MM vs 12.8 ± 1.97 g/dL in healthy controls; p = 0.045) and serum albumin (2.46 ± 0.9 g/dL in MM patients vs 4.63 ± 1.1 g/dL in healthy controls; p < 0.0001) when compared to healthy controls." (PMID 34522628, 2021). "In the present study, we found that albumin could bind to dimeric IgA in the sera of patients with multiple myeloma." (PMID 33578917, 2021). "The international staging system (ISS), based on serum beta-2 microglobulin and albumin, is used to predict survival in multiple myeloma, but its prognostic significance in diffuse large B-cell lymphoma (DLBCL) remains unknown." (PMID 29051524, 2017). "In addition, the pre-treatment albumin level played the most important role in survival capacity, especially within 22 months after anti-myeloma treatment." (PMID 26053837, 2015).